CD28 (CD28 molecule)
Diseases named in the same sentence as CD28 in open-access papers (continued):
Sharing a sentence is not in itself a finding about the gene and the disease.
tumor (continued). "CD8+CD107a+ T cells, CD8+CD28+ T cells (tumor-suppressive subtypes), and CD8+CD122+ T cells (tumor-promoting subtype) were detected in both TME and peripheral blood." (PMID 36333670, 2022). "Luc90-CAR-T reduced tumor burden and significantly extended survival of tumor bearing mice compared to controls when tested in both a third generation (CD28/4-1BB) and a 4-1BB only second-generation format." (PMID 35422095, 2022). "On the other hand, CD28-costimulated CAR-T cells are linked to more rapid T-cell proliferation and tumor eradication." (PMID 36505428, 2022). "CD79A/CD40 co-stimulated CAR-T cells also had superior anti-tumor activity and proliferative activity compared to CD28 or 4-1BB co-stimulated CAR-T cells in mice inoculated with Raji tumor cells." (PMID 35053463, 2022). "Replacement of the CD28 transmembrane domain with a CD8α domain reduced cytokine levels and improved clinical toxicity profiles with retention of anti-tumor activity." (PMID 36139142, 2022). "At the cellular level, scRNA-seq and CyTOF of NSCLC patients revealed that while PD-1 and TIGIT were expressed throughout the CD8+ T cell compartment, CD226 and CD28 were co-expressed by distinct populations likely important for tumor immunity." (PMID 35263569, 2022). "Human PBMCs were activated by Dynabeads Human T activator CD3/CD28 for 4 days before the transplantation (activated PBMCs) to amplify the T cell population responsible for cytotoxicity of Tb535H against tumor cells." (PMID 36071464, 2022). "Recent findings demonstrated that CD28 co-stimulation was necessary for responses to PD-1 blockade in tumor rejection." (PMID 35193632, 2022). "In the group treated with anti-CAIX/CD28 releasing anti-PD-L1 IgG4, we found only local tumor advance, with tiny lesions restricted to the diaphragm of only one out of five animals." (PMID 35628256, 2022). "constructed second generation PSMA-CAR-T cells containing CD28 stimulating molecule, it showed stronger anti-tumor response in mouse models." (PMID 35860578, 2022). "CTLA4 primarily functions by indirectly diminishing signaling through the co-stimulatory receptor CD28, reducing immune responses to weaken self- and tumor antigens." (PMID 35330161, 2022). "Recent reports suggest that both CTLA-4 and PD-1 preferentially suppress CD28 signaling within the tumor, leading to reduced T cell activation, effector function, and metabolism." (PMID 35379805, 2022). "Co-transduction of a TIGIT : CD28 CSR together with a tumor-specific TCR or CAR into human T-cells, drove enhanced cytokine production and superior anti-tumor function in a xenograft model of established human melanoma tumors." (PMID 35432319, 2022). "On the opposite, in melanoma patients, CD28− CD8+ T cells expressing NK associated receptors (NKRs), are able to produce perforin, thus promoting an efficient anti-tumor response." (PMID 35328795, 2022). "Transduction of a CTLA-4:CD28 CSR into tumor-specific T cells, resulted in elevated IFN-γ and IL-2 production and enhanced antitumor effect without systemic autoimmunity." (PMID 35432319, 2022). "In CAR-T cells, GITR co-stimulation yielded a comparable or even more robust anti-tumor activity than CD28 or 4-1BB G2 EGFR-targeted CAR-T cells in various tumor cell lines, including SKOV-3, A1847, and BxPC3." (PMID 35053463, 2022). "Collectively, these results demonstrate that PD-L1-dependent CD28 costimulation is at least partially responsible for the anti-tumor activity of ALPN-202 in this model." (PMID 35379805, 2022). "The contribution of IDO1-induced KYN generation by tumor cells on PD-1 expression was evaluated using anti-CD3/anti-CD28 activated CD8+ lymphocytes." (PMID 34025677, 2021). "Labeled CD8+ T cells were stimulated with CD3/CD28 antibodies for 3 days in the presence of tumor‐infiltrating CD11b+ myeloid cells from the control vehicle or TP‐16 treated CT26 tumor‐bearing mice." (PMID 33283987, 2021).
tumor (continued). "CD8 + CD57 + T cells in peripheral blood which do not express CD27 and CD28 have enhanced cytotoxic potential, while CD27 and CD28 expressing CD8 + CD57 + T cells in tumor have impaired cytotoxic activity." (PMID 34952595, 2021). "CD3/CD28 Dynabeads and an EpCAM BiTE, which targets EpCAM on tumor cells and CD3ε on T cells, were included as positive controls for activation-induced cell death (AICD) and BiTE-induced T cell death." (PMID 33820820, 2021). "Together, these findings strongly suggest that CD27+CD28+ Temra cells reflect a unique ‘prequel’ of tumor-specific CD8+ T cell responses and can predict tumor prognosis and therapeutic efficacy of patients with cancer undergoing immunotherapy." (PMID 34593620, 2021). "Low infiltration of CD56+ and CD28+ cells, as well as high expression of IL-10 in tumor tissue, were related with increased invasiveness of NFPAs." (PMID 34257554, 2021). "In pharmacological studies, CD28-based CAR elicited anti-tumor activity more rapidly than 4-1BB-based CAR T cells that persisted longer in vivo." (PMID 35117999, 2021). "As an example, CARs of mesothelin scFv-CD3z and folate receptor alpha (FRα) scFv-CD28 have been introduced simultaneously, resulting in an improved tumor trafficking and reduction of toxicity." (PMID 34830003, 2021). "Other tumor antigen-targeting BsAbs, including B7-H3 × CD28 and PD-L1 × CD28, showed similar costimulatory activity." (PMID 34358141, 2021). "Tumor-derived Jurkat T cells preactivated with anti-CD2/CD3/CD28 antibodies and contacted with the micro-arc CaP coating for 14 days showed a 4.5-fold upregulation in hTERT expression compared with activated malignant cells cultured without test samples." (PMID 34279263, 2021). "This suggests that CD-28 signalling is also important in the proliferation of cytotoxic T cells responsible for anti-tumour responses in patients." (PMID 34141724, 2021). "High levels of ROS following TCR and CD28 stimulation enhance Treg cell-mediated tumor immunosuppression and attenuate anti-tumor T cell responses by stabilizing SENP3." (PMID 33732706, 2021). "Engagement of the antigen-specific TCR and CD28 costimulatory molecule by tumor cells or antigen-presenting cells triggers a T cell signaling cascade involving ZAP70, PI3K, and RAS pathways." (PMID 34054817, 2021). "CD80 is one of the most potent costimulatory molecules involved in tumor cell recognition and killing, is activated by CD28 or CTLA-4 binding, and can induce T cell proliferation and cytokine production." (PMID 34852825, 2021). "Human L1CAM-specific CAR T cells harboring short- or long-spacer CAR constructs with CD28 co-stimulation lysed significantly more tumor cells than CAR T cells using 4-1BB signaling at each time point analyzed." (PMID 33801448, 2021). "CD28/B7 mediated proliferation of CD8+ T cells is required for anti-tumour efficacy and occurs in TDLNs." (PMID 34141724, 2021). "The key requirement for this bifurcation is either timely upregulation or downregulation of the expression of CD27 and CD28 while re-expressing CD45RA, a hallmark of Temra, during tumor progression." (PMID 34593620, 2021). "We also observed upregulation of PD1 and TIM3 immune checkpoint molecules, indicative for exhaustion, on tumor-infiltrating L1CAM-specific CAR T cells with CD28 signaling." (PMID 33801448, 2021). "It is possible that CaP-coated Ti samples only enhanced preliminary stimulation of 14-day proliferative tumor cells with anti-CD2/CD3/CD28 antibodies." (PMID 34279263, 2021). "The results showed that PBK knockdown significantly increased the percentage of lysis TW03 cells when the tumor cells were cocultured with CD3/CD28-activated human HLA-A2+ T lymphocytes, and this increase was markedly reversed by the recovery of CD276." (PMID 33431797, 2021).
tumor (continued). "It belongs to the B7/CD28 family and acts by indirectly lowering signalling through the co-stimulatory receptor CD28, which also restores T cell-three-signal activation in the tumour, draining lymph nodes." (PMID 34660728, 2021). "Co-inhibitory CTLA-4 competes with co-stimulatory CD28 to bind to CD80 or CD86 on the surface of APCs to alleviate the anti-tumor immunity of tumor infiltrated T lymphocytes (TILs), such as CD4+T, CD8+T cells and regulatory T cells (Tregs)." (PMID 34858835, 2021). "The synergistic antitumor effect of anti-CTLA-4 in our systems relies on the reinvigoration of tumor-reactive CTLs by re-enabling CD28 co-stimulation with DCs." (PMID 34006895, 2021). "For instance, tumor models with high TGFβ within tumor tissue require an intact LCK motif within the CD28/CD3ζ CAR receptor in order to overcome TGFβ-mediated suppression." (PMID 34012443, 2021). "Although both murine L1CAM-specific CAR T cells with CD28 co-stimulus produced similar levels of cytokines upon stimulation in vitro, anti-tumor activity in vivo differed." (PMID 33801448, 2021). "Taken together, CD28 costimulation downregulates the release of soluble factor(s) by TCR-activated CD8+ T cells that suppresses the anti-tumor cytolytic function of CD8+ effector T cells." (PMID 34011962, 2021). "Unstimulated, CD3/CD28 beads- (TCR signal) or U251-CD133OE tumor cell-activated (CAR signal) anti-CD133 CAR T cells were treated with BAY 60-6583 or vehicle control for 16 h." (PMID 33776765, 2021). "Together, these data indicate that dual CD28 and 41BB co-stimulation provided by pCAR-M/34 results in metabolic remodeling and enhanced resistance to tumor-induced T cell dysfunction." (PMID 35028604, 2021). "The affinity of B7 proteins for CTLA-4 is much higher than for CD28, and for the tumour cell expressing these proteins, the net result is lymphocyte anergy and apoptosis." (PMID 32929195, 2021). "Preactivation of Jurkat T cells with anti-CD2/CD3/CD28 antibodies that mimic the stimulating signal produced by APCs led to a statistically increased viability of tumor-derived cells after 14 days of culture." (PMID 34279263, 2021). "CARs from 2G or 3G containing the 4-1BB domain have been reported to have greater in vivo expansion and anti-tumor activity compared to CD28 2G CARs." (PMID 34771581, 2021). "Tumor-derived Jurkat T cells preactivated with anti-CD2/CD3/CD28 antibodies strongly responded to the micro-arc CaP coating and showed a 4.5-fold upregulation of hTERT gene expression after 14-day culture." (PMID 34279263, 2021). "Engagement of B7 ligands, notably B7-1 (CD80) and B7-2 (CD86), on antigen-presenting cells with CD28 co-stimulatory receptors on T cells stimulates the proliferation and activation of CTLs, which subsequently elicits an anti-tumor immune response in the host." (PMID 34541363, 2021). "As CTLA-4 has a stronger binding affinity for B7 ligands than does CD28, CTLA-4 competitively inhibits the ligation of B7 and CD28, thereby attenuating T cell proliferation and activation, and suppressing anti-tumor immunity." (PMID 34541363, 2021). "In this study, we found that mice inoculated with CD73-negative B16.gp33 tumor cells have significantly higher CD73 on CD28−CD8+ T cells than on CD28+CD8+ T cells that were isolated from the draining lymph nodes, as well as from tumor." (PMID 34011962, 2021). "Clearly, future studies should focus on directly comparing MGA271 scFv-based B7-H3-CARs with different costimulatory domains, including CD28, 41BB, and others, in this model to fully understand the different tumor control capacities of these CARs." (PMID 34211478, 2021). "Blocking the negative regulators of PD-1 and CTLA4 that impair CD28 signaling to inhibit T cell release facilitates anti-tumor activity." (PMID 34208157, 2021). "As with the anti-CD3 and anti-CD28 stimulation, the effect of anti-PD-1 antibodies was only seen in the tumor-infiltrating MAIT cells." (PMID 33885944, 2021).
tumor (continued). "Shin et al7 reported that the cytotoxic T-lymphocyte-associated protein 4 (CTLA4)-CD28 chimera, consisting of the extracellular and transmembrane domains of CTLA4 and the cytoplasmic domain of CD28, enhanced the activity of tumor-specific T cells." (PMID 34853180, 2021). "The incorporation of costimulatory domains, such as CD28 or 4-1BB (CD137) for enhanced survival and proliferation render the CAR T-cells less susceptible than unmodified T cells to negative regulation from tumor cells." (PMID 33442419, 2021). "As expected, the positive control of αCD3/CD28 beads stimulated IFN-γ production in > 80% of Tc cells isolated from the tumor-free peripheral blood samples (Ag-naive PBMC)." (PMID 34092233, 2021). "Soluble B7-1 anti-tumor effects were mainly mediated by the activation of downstream signaling components of the CD28 and T cell receptor pathways including EGR1–4, NF-κB and MAPK." (PMID 34531847, 2021). "CD40L:CD28-transgenic T cells induced similar effects on ercDCs, which are tumor-conditioned myeloid cells found in human RCC." (PMID 34912334, 2021). "This suppressive effect was characterized by the loss of CD27/CD28 co-stimulatory molecules and the decrease of IFN-γ production, in accordance with the phenotype presented by T cells on HNSCC tumor biopsies." (PMID 33804419, 2021). "If this is the case, the superior function of CD28- compared to 4-1BB-incorporating CAR T cells would only become apparent when tumors with an established tumor stroma are treated." (PMID 33801448, 2021). "Here we show that CAR T cells targeting L1CAM with CD28 signaling more effectively control tumor growth than CAR T cell designs using 4-1BB signaling." (PMID 33801448, 2021). "In vitro, this human PD1:CD28 was shown to respond to programmed death-ligand 1 (PD-L1)-expressing tumor cells and transduce activation signals through the chimeric receptor to augment CD8+ T cell proliferation, cytokine production and cytotoxic function." (PMID 34344725, 2021). "Subsequently, binding of the CD28 co-stimulatory receptor to the DCs’ CD80/86 receptor fully activates the cytotoxic T cells which then migrate to infiltrate the tumour and kill the cells by locally releasing perforin and granzymes." (PMID 34638471, 2021). "Accordingly, we demonstrated that the relative proportion of CD27+CD28+ Temra inversely correlates with the number of CD8+ TILs and tumor mutation burden (TMB), known to affect the generation of neoantigens and the number of tumor-reactive CD8+ TILs." (PMID 34593620, 2021). "H9 cell, a normal human T lymphocyte line, can be activated into effector T cells that kill tumor cells using a CD3/CD28 antibody." (PMID 34249750, 2021). "For example, results of a recent study indicate that blockade of PD-L1 interaction with B7-1 in trans can augment tumor immunity via down-regulating the effect of PD-L1 interaction with PD-1 that also required CD28-dependent activation." (PMID 34531847, 2021). "CD28, a co-stimulatory molecule essential for T cell activation is also present in both tumor types but only significantly increased in MNG compared to normal brain control." (PMID 35366268, 2021). "We activated PBMCs with anti-CD3/CD28 beads in order to simulate activation of T cells with tumor antigen." (PMID 33446805, 2021). "As an essential co-stimulatory, CD28 on CD8+ T cells interacts with B7 molecules on antigen-presenting cells to activate the anti-tumor immune response of CD8+ T cells to tumor antigens." (PMID 33777727, 2021). "Previous studies had reported that CTLA4-CD28 chimera gene-modified T cell, which the intracellular signaling domain of CTLA4 was replaced with the CD28 signaling domain, showed significantly enhanced anti-tumor effect in murine tumor models." (PMID 33868277, 2021). "L1CAM-targeting short spacer-CD28/ζ CAR T cells expanded the most at the tumor site and induced initial tumor regression." (PMID 33801448, 2021).
tumor (continued). "Here, by use of Hepa1.6.gp33 in vitro killing assay and B16.gp33 tumor mouse model we demonstrate that CD28 engagement during TCR ligation prevents CD8+ T cells from becoming suppressive." (PMID 34011962, 2021). "Human CD38-directed nanobodies incorporated into a CAR particle (anti-CD38Nb.CD28.4-1BB.CD3ζ.CAR-NK92) demonstrated anti-tumor activity." (PMID 34072732, 2021). "Various cytokines, such as IL-13, IL-15, and IL-32, and surface proteins, including CD47, CD40, and CD28, provide the direct molecular bridge between tumor cells and adjacent cells, resulting in tumor progression." (PMID 34830466, 2021). "CAR is composed of different domains, including (i) the single-chain variable fragment (scFv) of tumor antigen-specific Ab, (ii) a hinge region, (iii) the trans-membrane domain of CD8α or CD28 molecules and (iv) the intracellular signaling region." (PMID 33450862, 2021). "The immune checkpoint CTLA-4 (cytotoxic T-lymphocyte-antigen 4), which inhibits the co-stimulatory CD28 signal on T cells, has been recently found expressed on other cell populations, such as tumor and natural killer (NK) cells." (PMID 32024070, 2020). "Lymphocytes entering the tumor have been shown to downregulate costimulatory molecules such as CD28 and CD62L." (PMID 33178210, 2020). "CARs are synthetic chimeric receptors consisting of an antibody based extracellular part to recognize specific antigens expressed on the surface of tumor cells and an intracellular part containing (co)stimulatory signals derived from CD3ζ, CD28 and/or 4_1BB." (PMID 32019116, 2020). "Both CD80 and CD28 blockade significantly impaired the anti-tumor efficacy of BI 853520, implying an important role for CD80 in regulating response to a FAK inhibitor." (PMID 31959281, 2020). "To search for putative tumor-associated antigens in the early transformation phase, we similarly activated purified normal CD4+ T cells via CD3/CD28 beads and transduced them with lentiviral vector expressing NA or KD." (PMID 33348781, 2020). "Agonistic antibodies and/or RNA aptamers targeting receptors including 4-1BB, OX40, CD40, GITR, ICOS and CD28 are in pre-clinical development, and have shown anti-tumor activity in mouse models of cancer." (PMID 31959281, 2020). "In parallel, naive CD8+ T lymphocytes can be primed (i.e., co-stimulation of TCR-I and CD28) by mature DCs presenting tumor antigen epitopes onto MHC-I molecules and turned into cytotoxic precursors (preCTL)." (PMID 33281620, 2020). "Surprisingly, we didn’t observe any PD-L1 up-regulation of CARPD-L1z T cells either activated by CD3/CD28 antibodies or co-cultured with PD-L1+ tumor cells, even the percentage of CD25 and CD69 double-positive T cells confirmed they fully activated." (PMID 32514352, 2020). "CD28 anti-MUC-1 CAR exploiting the variable fragments of another tumor-specific antibody (TAB004) was used in a preclinical study published in Cells in 2019." (PMID 35582441, 2020). "In vivo, murine studies have shown that PD-1 upregulation within the tumor microenvironment impeded the function of CD28-CAR-T cells, which was restored by concomitant treatment with anti-PD-1 antibodies." (PMID 33008037, 2020). "We also investigated the production of IFN-γ and the degranulation activity (CD107+) by MC38 tumor-derived T cells on ex vivo stimulation with beads coated with α-CD3/CD28 antibodies." (PMID 32461349, 2020). "The co-expression of T-bet with a second-generation CAR (CD28.CD3ζ) targeting the B7-H3 antigen has been shown to potentiate CAR T-cell anti-tumor activity." (PMID 33374128, 2020). "Right – subcutaneous tumor growth of SCC7.1 cells treated with either Vehicle or 50 mg/kg BI 853520 ± 100 μg anti-CD28 antibody." (PMID 31959281, 2020).